HNRNPC (heterogeneous nuclear ribonucleoprotein C)
Diseases named in the same sentence as HNRNPC in open-access papers (continued):
Sharing a sentence is not in itself a finding about the gene and the disease.
colorectal adenocarcinoma (1 paper, 2022). The most common type of colorectal carcinoma. "Immunohistochemical staining revealed that hnRNPA1, hnRNPA2B1, hnRNPC, hnRNPK, hnRNPR, and hnRNPU are overexpressed in colorectal adenocarcinoma." (PMID 35875075, 2022). "By using IHC staining of 10 human colorectal adenocarcinoma specimens, we confirmed that hnRNPA1, hnRNPA2B1, hnRNPC, hnRNPK, hnRNPR, and hnRNPU were mainly localized in the nucleus and had higher expressions in colorectal adenocarcinoma tissues compared with adjacent normal tissues (ANT)." (PMID 35875075, 2022).
depression (1 paper, 2022). "Next, we performed differential gene analysis of m6A regulators in depression and found that FTO, RBM15B, METTL3, LRPPRC, HNRNPC, ZC3H13, and YTHDF2 were significantly upregulated in depressed rats." (PMID 35480327, 2022).
Hepatic hemangioma (1 paper, 2023). A congenital vascular malformation in the liver composed of masses of blood vessels that are atypical or irregular in arrangement and size. "Subsequently, compared with hepatic hemangioma tissues, HNRNPC expression was also significantly increased in HCC with metastasis tissues, and metastatic HCC tissues respectively based on GSE40367 database." (PMID 37469973, 2023).
Intellectual disability (1 paper, 2025). "Haploinsufficiency of HNRNPC, an RNA binding protein called heterogeneous nuclear ribonucleoprotein C, affects the alternative splicing of multiple intellectual disability-associated genes, as HNRNPC is involved in RNA processing." (PMID 41191133, 2025).
male infertility (1 paper, 2025). The inability of the male to effect fertilization of an ovum after a specified period of unprotected intercourse. "Taken together, these results suggest that hnRNPC depletion in the testis impairs meiotic initiation and progression, thereby leading to defective spermatogenesis and male infertility." (PMID 39921484, 2025).
microphthalmia (1 paper, 2025). Congenital or developmental anomaly in which the eyeballs are abnormally small. "We report the second subject carrying the pathogenic c.296G>A missense variant (Arg99Gln) in HNRNPC showing a unique clinical presentation characterized by DD/ID, distinctive facial features, cochlear aplasia, and bilateral colobomatous microphthalmia." (PMID 40004505, 2025).
osteosarcoma (1 paper, 2021). A usually aggressive malignant bone-forming mesenchymal neoplasm, predominantly affecting adolescents and young adults. "Based on two large-scale cohorts, HNRNPA2B1, HNRNPC, RBM15, YTHDF1, and YTHDC1 expression levels are upregulated in osteosarcoma tissues." (PMID 34094986, 2021).
ovarian serous cystadenocarcinoma (1 paper, 2021). A malignant serous cystic epithelial neoplasm arising from the ovary. "The expression of YTHDF1, HNRNPC, IGF2BP1, VIRMA, and HNRNPA2B1 was significantly positively correlated with the ovarian serous cystadenocarcinoma (OV) tumor stem cell score (based on DNA methylation) (DNAss)." (PMID 34150845, 2021).
progressive supranuclear palsy (1 paper, 2022). A rare late-onset neurodegenerative disease characterized by supranuclear gaze palsy, postural instability, progressive rigidity, and mild dementia. "Intriguingly, high hnRNPC expression level is associated with progressive supranuclear palsy (PSP), a sporadic tauopathy with pathological accumulation of Tau species that contain exon 10, which suggests a putative therapeutic role of hnRNPC for PSP treatment." (PMID 34965173, 2022).
psoriasis (1 paper, 2024). An autoimmune condition characterized by red, well-delineated plaques with silvery scales that are usually on the extensor surfaces and scalp. "The roles of other genes, including ZC3H13, HNRNPC and YTHDC1, in psoriasis have not yet been explored." (PMID 38436011, 2024).
rectal carcinoma (1 paper, 2021). A malignant epithelial neoplasm that arises from the rectum and invades through the muscularis mucosa into the submucosa. "HNRNPA2B1 and HNRNPC are mainly related to Astler–Coller B1 rectal carcinoma." (PMID 34778266, 2021).
schizophrenia (1 paper, 2019). A major psychotic disorder characterized by abnormalities in the perception or expression of reality. "Additionally, we found changes in hnRNPC levels in the temporo-posterior gyrus of patients with schizophrenia." (PMID 30890939, 2019). "We also found altered levels of hnRNPC, hnRNPK and hnRNPU in post mortem samples of the anterior temporal lobe (ATL) from patients with schizophrenia." (PMID 30890939, 2019).
squamous cell carcinoma (1 paper, 2021). A carcinoma arising from squamous epithelial cells. "In addition, we found only WTAP and HNRNPC were up-regulated in squamous cell carcinoma compared to adenocarcinoma." (PMID 33748145, 2021).
steatosis (1 paper, 2022). Increased lipid within the cytoplasm of cells. "RBM15, YTHDC2, HNRNPC, HNRNPA2B1, and EIF3H were related to steatosis." (PMID 36120320, 2022).
sterility (1 paper, 2025). "To determine the cause of sterility in hnRNPC cKO males, we conducted histological analyses and found that pachytene‐like spermatocytes were the most advanced spermatogenic cells in hnRNPC cKO adult testes, and no mature spermatozoa were observed in hnRNPC cKO cauda epididymis." (PMID 39921484, 2025).
tauopathy (1 paper, 2022). Neurodegenerative disorders involving deposition of abnormal tau protein isoforms (tau proteins) in neurons and glial cells in the brain. "Specifically, we found the hnRNPC that we validated to promote 4 R-Tau expression is also upregulated in PSP at the transcript level, a sporadic 4 R-Tauopathy, which suggests the putative correlation between hnRNPC expression and disease progression of PSP." (PMID 34965173, 2022).
triple-negative breast carcinoma (1 paper, 2021). An invasive breast carcinoma which is negative for expression of estrogen receptor (ER), progesterone receptor (PR), and human epidermal growth factor receptor 2 (HER2). "Independent of hnRNPC targeting, a recent study described spliceosome inhibition in triple-negative breast cancer with MYC-driven hyperactivated transcriptional activity." (PMID 34297039, 2021).
viral hepatitis (1 paper, 2025). An acute or chronic inflammation of the liver parenchyma caused by viruses. "Despite advances in understanding canonical m6A readers such as YTHDF1–3 and YTHDC1/2, the functions of noncanonical readers – such as IGF2BP1–3, HNRNPC, and HNRNPG remain largely unexplored in the context of viral hepatitis." (PMID 40793828, 2025).
tumor (117 papers, 2013 to 2025). "Increased HNRNPC expression was found to be significantly associated with advanced tumor stage and metastasis." (PMID 41154660, 2025). "In this research, we investigated the association between HNRNPC expression and these tumor-related factors across diverse cancer types." (PMID 39735682, 2025). "Accumulating evidence suggests that HNRNPC functions as an oncogene, and its elevated expression is associated with tumor growth and metastasis in various cancer types, including PCa." (PMID 41187218, 2025). "The observed correlations with immune cell infiltration, immune regulatory genes, and pathway scoring further underscore HNRNPC’s intimate association with tumor immunity and its therapeutic target’s potential." (PMID 39735682, 2025). "Among 28 tumor types, including LUSC, THCA, and LIHC, higher HNRNPC expression levels were associated with younger age groups, whereas in 9 tumor types, including LUSC, PAAD, and BRCA, higher expression levels were observed in older age groups." (PMID 39735682, 2025). "Our study reveals that HNRNPC, an alternative splicing (AS) factor and m6A reader, increases tumor-related variants through m6A-dependent manner, thereby promoting lymphatic metastasis in CCa." (PMID 39375330, 2024). "Heterogeneous nuclear ribonucleoprotein C1/C2 (HNRNPC) and RhoA have been implicated in the regulation of tumour cell proliferation and chemo‐ and radioresistance." (PMID 35277915, 2022). "Correlations of HNRNPC protein levels with clinicopathological features in HCC were analyzed by chi-square test; this demonstrated that HNRNPC protein levels were significantly associated with tumor size (P = 0.007) and tumor TNM stage (P=0.028)." (PMID 33937074, 2021). "In both training and validation cohorts, YTHDC2 was associated with tumor stage (P<0.01), while HNRNPC was up expressed in progressed tumor (P<0.05)." (PMID 32398949, 2020). "This transcript regulates tumor proliferation and its gene target hnRNPC (Heterogeneous nuclear ribonucleoproteins C) encodes for a SSc-associated auto-antigen." (PMID 30866419, 2019). "Increased KHSRP and HNRNPC expression was significantly associated with advanced tumor stages and metastasis (both lymph node and distant)." (PMID 31775888, 2019). "As an m6A “reader,” HNRNPC belongs to the subfamily of ubiquitously expressed heterogeneous nuclear ribonucleoproteins (hnRNPs) and is implicated in oncogenic functions in various tumor." (PMID 36093132, 2022). "Similarly, HNRNPC knockdown caused an obvious increase of tumor-infiltrating CD8 positive T cells, along with elevated CD4 positive T cells." (PMID 36536402, 2022). "Taken together, these results robustly established the tumor-associated role of HNRNPC in pRCC." (PMID 35502201, 2022). "Moreover, HNRNPC is involved in aberrant splicing and implicated in the formation of the tumour transcriptome." (PMID 34044876, 2021). "Specifically, we noted a notable positive correlation between HNRNPC expression and most immune cell populations across diverse malignancies, proposing a probable involvement of HNRNPC in sculpting the tumor immune microenvironment." (PMID 39735682, 2025). "We did not conduct comprehensive transcriptomic and proteomic analyses, which limited our detailed exploration of HNRNPC’s functions in tumor cells." (PMID 39735682, 2025). "After detecting the HNRNPC protein levels in subcutaneous tumor tissues using Western blot, it was found that the HNRNPC protein amount in the knockdown group was significantly lower than that in the control group." (PMID 39735682, 2025). "In PCa, elevated HnRNPC expression is closely correlated with tumor stage, tumor grade and the overall survival." (PMID 39268470, 2024). "HNRNPC is upregulated in diverse cancers and HNRNPC silencing significantly suppressed BC-cell proliferation and tumor growth." (PMID 39054967, 2024). "HNRNPC is an RNA binding protein that has been reported to regulate m6A modification in tumor development." (PMID 37106446, 2023).
tumor (continued). "Malat1 has been shown to control the cell cycle in tumor cells by interacting with heterogeneous nuclear ribonucleoprotein C (hnRNP C)." (PMID 36883566, 2023). "HnRNPC, hnRNPK, and hnRNPU induced the expression of the inflammatory nitric oxide synthase 2 (Nos2), an enzyme involved in tumor metastasis through the production of reactive oxygen species, in a bacteria-infected RAW264.7 mouse macrophage cell line." (PMID 36982162, 2023). "Since HNRNPC was reported to regulate cancer progression through diverse systems, the specific mechanisms of its tumor-promoting role in pRCC came as an unavoidable concern." (PMID 35502201, 2022). "It was obvious from this results that hnRNPC knockdown cells reduced tumor weight and size in mice injected." (PMID 35355828, 2022). "In tumour cells, expression of hnRNPC is reduced, therefore exon 4 is included resulting in elevated levels of Grb2 and reduced expression of the negative regulator Grb3-3." (PMID 36171279, 2022). "On the other hand, tumor weight and size increased dramatically in mice injected with cells overexpressing hnRNPC." (PMID 35355828, 2022). "Immunostaining of tumor samples confirmed that hnRNPC was highly expressed in PDAC tissue samples compared to the adjacent noncancerous pancreatic tissues." (PMID 35355828, 2022). "We discovered that a correlation existed between higher HNRNPC expression and deeper tumor invasion (P = 0.009), and a correlation between greater HNRNPC expression and an elevated probability of lymph node metastasis (P = 0.011)." (PMID 36536402, 2022). "The results revealed significant correlations between HNRNPC expression levels and tumor infiltration (P = 0.019) and recurrence (P < 0.001), while ZEB1 expression was significantly correlated with recurrence (P < 0.001)." (PMID 35963855, 2022). "Next, through the survival analysis, we revealed that high HNRNPC expression in 30 tumor tissues predicted a poor prognosis for NSCLC patients (P < 0.05)." (PMID 36536402, 2022). "In seven pRCC samples obtained from our cohort, HNRNPC mRNA level was statistically upregulated in tumor tissues than normal tissues." (PMID 35502201, 2022). "The nomogram and calibration curves of prediction model demonstrated that HNRNPC expression was well qualified to predict tumor stage and overall survival of pRCC patients as an independent risk factor." (PMID 35502201, 2022). "Yellow background indicated the most significant (p < 0.0001) genes up-regulated in tumor tissues, including HNRNPC, YTHDF1, IGF2BP1, YTHDF2, RBM15, and IGF2BP3." (PMID 35581263, 2022). "hnRNPC expression was significantly diminished in the tumour tissue relative to the surrounding normal colonic tissue." (PMID 36171279, 2022). "In mouse xenograft models, the results were consistent with our in vitro data and showed that knockdown of HNRNPC inhibited the tumor growth and metastasis in vivo, suggesting an oncogene role of HNRNPC in NSCLC development." (PMID 36536402, 2022). "That the hnRNPC-IQGAP3 pathway is an important regulator of PDAC tumor growth has been validated by these findings." (PMID 35355828, 2022). "Next, to observe the role of HNRNPC in tumor metastasis in vivo, stable HNRNPC-knockdown cells (H1299) were transfected with luciferase plasmids and then injected into the tail veins of nude mice." (PMID 36536402, 2022). "According to previous studies, HNRNPC has been reported to regulate immunosuppressive events in tumor microenvironment, and we conducted comparable analyses on HNRNPC to uncover its role in immune systems." (PMID 35502201, 2022). "We found that tumor volume increased in mice overexpressing hnRNPC, whereas tumor volume decreased in mice injected with hnRNPC knockdown cells, relative to their significant controls." (PMID 35355828, 2022).
tumor (continued). "Although a handful of isomiRs were dysregulated in our LIHC samples, there should be more oncogenic or tumor-suppressing isomiR candidates in other cancers in which RBPs, such as hnRNPC and U2AF2, are dysregulated." (PMID 35729324, 2022). "Result showed that LINC00924 overexpression effectively promoted intraperitoneal tumor dissemination, and hnRNPC knockdown rescued LINC00924-induced intraperitoneal tumor dissemination." (PMID 36418856, 2022). "Through further analysis, the absolute expression of HNRNPC in tumor tissues was the highest, and the absolute expression of YTHDC2 was the lowest." (PMID 35581263, 2022). "The subsequent examination of clinical tumor samples will provide fresh light on the role of HNRNPC in tumorigenesis." (PMID 35344508, 2022). "Using immunohistochemistry, we further assessed the tumor samples for expression of hnRNPC, IQGAP3, and Ki-67." (PMID 35355828, 2022). "As a differentially upregulated gene in multiple tumor types or cancer cell lines, HNRNPC can promote cancer development and mediate RNA splicing." (PMID 35963855, 2022). "The IGF2BP3 and HNRNPC expression in different subtypes of the stage, molecular, and immunity was analyzed using an integrated repository portal for tumor-immune system interactions (TISIDB)." (PMID 33796449, 2021). "In the present study, we showed that HNRNPC protein levels were statistically higher in HCC tumor tissues than in para-tumor tissues by western blotting and IHC." (PMID 33937074, 2021). "On the contrary, METTL3, KIAA1429, RBM15B, HNRNPA2B1, and HNRNPC had significantly higher expression in tumor tissues (p < 0.001)." (PMID 34277622, 2021). "The IHC results showed high expression of HNRNPC protein, mainly located in nuclei, in 80 of 147 tumor tissues (54.40%) and in 13 (15.90%) of 82 paired para-tumor tissues (P<0.001)." (PMID 33937074, 2021). "In the present study, we used western blotting, immunohistochemistry (IHC), and bioinformatics analysis to demonstrate that HNRNPC had significantly elevated expression in HCC tumor tissues compared with para-tumor tissues." (PMID 33937074, 2021). "HNRNPC protein levels were obviously higher in tumor tissues than in para-tumor tissues, based on western blot analysis of 12 HCC tumor tissues and their matched para-tumor tissues (P< 0.001)." (PMID 33937074, 2021). "As an alternative strategy, our work also elevates tumor-specific targeting of hnRNPC as a means to enhance cancer immunotherapy." (PMID 34297039, 2021). "We found that the expression of IGF2BP2, RBMX, and HNRNPC was correlated with various activated cancer-related pathways, providing insight into the molecular mechanisms related to tumor progression." (PMID 33816266, 2021). "Similar to the results of Li’s report, we found that KIAA1429, METTL3, and HNRNPC are highly expressed in HCC tumor samples." (PMID 32903675, 2020). "Heterogeneous nuclear ribonucleoprotein C (HNRNPC) is up-regulated in multiple tumors or tumor cell lines." (PMID 33633744, 2020). "In our eight mRNAsi based signature, high expression of RGS16, LYVE1, hnRNPC, ANP32A, and AIMP1 are correlated with a high risk of death as these genes focus in promoting cell proliferation and tumor progression, similar to stem cells." (PMID 33329703, 2020). "Using these data, we determined the mean reads per million overlapping with the hnRNPC 3′ exon across all tumour samples and across all normal samples." (PMID 31147722, 2019). "More importantly, our investigation reveals that high expression levels of KHSRP and HNRNPC are significantly correlated with tumor metastasis and serve as independent prognostic factors for the poor outcomes of NSCLC patients." (PMID 31775888, 2019). "Similar to the cell-based system, this analysis revealed elevated expression of hnRNPC in the tumour compared to the normal samples." (PMID 31147722, 2019).